GHR (growth hormone receptor)
Diseases named in the same sentence as GHR in open-access papers (continued):
Sharing a sentence is not in itself a finding about the gene and the disease.
tumor (continued). "They considered current treatment outcome goals with a focus on the impact of current and emerging somatostatin receptor ligands, growth hormone receptor antagonists and dopamine agonists on biochemical, clinical, tumour mass and surgical outcomes." (PMID 30050156, 2018). "Multiple studies have also reported nuclear localization of GHR, indicating an intracrine role of GH, also considered being particularly relevant in upregulation of tumor proliferation." (PMID 28223541, 2017). "Similar to the human tumor, the GHR was expressed both in diffuse and spot patterns mainly in the cytosol." (PMID 27267119, 2016). "Like the GHR, GH expression is higher in cancerous than normal prostate cell lines, and GH immunoreactivity increases in parallel with IL-6 expression and tumor progression." (PMID 25580121, 2014). "After rhGH treatment, tumor growth was significantly increased in SGC-7901 (GHR(+++)) tumor-bearing mice, However, in MKN-45 [GHR(-)] tumor-bearing mice, tumor growth was not significantly increased by rhGH." (PMID 23554765, 2012). "A significant correlation was found between GHR expression and tumor stage (P < 0.001) and tumor differentiation (P < 0.001)." (PMID 23554765, 2012). "Despite that significant assoication between GHR expression levels was detected by immunohistochemistry and RT-PCR, a significant assoication between GHR expression and tumor grade, and tumor differentiation was found only with immunohistochemistry." (PMID 23554765, 2012). "A significant inverse correlation was found between GHR expression and the tumor stage (P < 0.001), and tumor differentiation (P < 0.001)." (PMID 23554765, 2012). "GHR-KO mice also had decreased tumour incidence, reduced tumour burden, less severe pulmonary adenocarcinomas and an age-related delay in fatal neoplastic diseases relative to controls." (PMID 21115536, 2011). "Given that pharmacologic inhibition of GHR with pegvisomant effectively mitigated these pro-tumorigenic effects, additional inhibitors of GH action potentially qualify as strategies to enhance chemotherapy efficacy and limit tumor progression in NSCLC." (PMID 41515995, 2025). "Therefore, suppressing both GHR and PRLR by a dual antagonist like compound-D or S1H can have a wider range of anti-tumor effects than GHR-specific inhibition by pegvisomant." (PMID 41515995, 2025). "In the present study, we hypothesized that targeting GHR in NSCLC could significantly mitigate tumor resistance to anticancer therapies." (PMID 41515995, 2025). "However, upon further analysis of the correlation between GHR expression and tumor stage, we found that GHR expression is significantly positively correlated with increasing tumor stage (rho = 0.144, p = 0.00359)." (PMID 40806252, 2025). "Blocking the GHR action attenuates this process, making the tumor cells drug sensitive." (PMID 39123364, 2024). "According to our results, we may speculate that the GHR isoform may be integrated to clinical, genetic, and molecular and morphological tumor biomarkers, for an individual patient tailored therapy." (PMID 39280003, 2024). "Also, GHR is expressed not only in epithelial cells but also activates fibroblasts in the tumor stroma of normal and neoplastic mammary tissue in dogs." (PMID 39459020, 2024). "Moreover, in human PDAC patients, GHR expression strongly correlates with a gene signature of tumor promotion and immune evasion, which corroborate with that in syngeneic tumors in wild-type vs. GH transgenic mice." (PMID 39000545, 2024). "In the human PDAC patient tumor transcriptome (TCGA), we identify strong and significant correlations between tumoral GHR expression and known lymphangiogenic (LYVE1, FLT4, VEGFC, and PDPN) and angiogenic (PDGFRa, FGFR1, TGFB3, TGFB1, TGFBR2, HIF1a, IL6, and IL1B) markers." (PMID 39000545, 2024).
tumor (continued). "In addition, several components of the TME express GH and GHR and have well-characterized GH-regulated phenotypes, which are tumor-supportive, therapy-refractory, and immune-suppressive." (PMID 39000545, 2024). "Most tumor cells express GH, which may indicate that the autocrine function of GH on tumor cells activates GHR more than GH secreted by the pituitary gland, thereby driving cancer progression." (PMID 36945046, 2023). "Furthermore, constitutive nuclear localisation of the GHR in murine pro-B cells resulted in metastatic tumours when injected into nude mice suggesting a role in tumorigenesis and tumour progression." (PMID 37043098, 2023). "In‐line with the tumour‐promoting role of GHR demonstrated in this study using several GBM models, targeted inhibition of GHR signalling using the prototypic GH antagonist GH‐G120K impaired GBM cell migration in vitro and decreased cell viability in PDCLsGHR high only." (PMID 35808822, 2022). "Moreover, we report that GHR mRNA expression is enriched in the infiltrative tumour of patient GBM compared to the core of the tumour." (PMID 35808822, 2022). "Also decreased hepatic expression of GHR was associated with increased serum levels of AFP, large tumor size, vascular invasion, advanced histo-pathological stage, and worse outcome." (PMID 36374927, 2022). "Despite these results, further research is needed to examine whether GHR functions as a tumor suppressor and whether GHR depletion leads to tumor development in vivo." (PMID 35729324, 2022). "Collectively, these data suggest that GH/GHR signaling contributes to HCC pathogenesis and, therefore, that targeting GHR could be considered a potential approach to eradicate this aggressive neoplasm." (PMID 36276070, 2022). "We tested the hypothesis that GHR could represent a potential therapeutic target in this aggressive neoplasm." (PMID 36276070, 2022). "Our findings may also lead to future studies exploring the targeting of GHR signaling in other aggressive neoplasms." (PMID 36276070, 2022). "In GBM patient‐derived cell lines, GHR signalling modulates the expression of proteins involved in cellular movement, promotes cell migration, invasion and proliferation in vitro and promotes tumourigenesis, tumour growth, and tumour invasion in vivo." (PMID 35808822, 2022). "Moreover, we reported that decreased expression of GHR was significantly associated with serum AFP level>100 ng/ml (p = 0.048), increased tumor size (p = 0.02), vascular invasion (p = 0.002), and advanced pathological stage (p = 0.01)." (PMID 36374927, 2022). "After 24 days, tumour volume was remarkably inhibited by GHR blockage in mouse models." (PMID 33492754, 2021). "Furthermore, we detected the GHR, PCNA (one tumour growth marker) and PI3K/AKT levels in tumours derived from cells silenced GHR and found the expression of GHR still decreased in the dissected tumours." (PMID 33492754, 2021). "In summary, these results suggested that GHR silence inhibited tumour growth in animal model." (PMID 33492754, 2021). "Thus, GHR promoted OS cell proliferation and tumor growth by inhibiting cell cycle arrest and suppressing cell apoptosis." (PMID 31725956, 2020). "Collectively, these results revealed that knockdown of GHR could inhibit OS cell colony formation and reduce tumor growth." (PMID 31725956, 2020). "GHR knockdown in these cells reduced tumor progression and sensitized the tumors to DT." (PMID 30617282, 2019). "Thus, our results at both excess GH and GHR depletion, show that the GH-GHR pair regulates aggressive tumor phenotypes by exerting extensive control over the activation states of important oncogenic signaling mediators." (PMID 28223541, 2017). "To evaluate whether exogenous GH treatment could modulate cell proliferation in the tumor cell lines, we first confirmed GHR expression, both by immunodetection of the receptor and by real-time PCR." (PMID 26670463, 2015).
tumor (continued). "GHR expression was significantly correlated with tumor differentiation and tumor grade." (PMID 23554765, 2012). "While tumoral GH1 expression can provide some insight into GH action, it may not be as reliable as an indicator of active GH signaling as GHR expression, since GHR levels more directly reflect a tumor’s capacity to respond to circulating GH and activate downstream signaling pathways." (PMID 40806252, 2025). "However, in human PDAC patients (179 samples, TCGA database), mean tumor GHR expression is 4-fold higher than that in untransformed ductal and acinar cells and comparable to the mean GHR expression of the normal whole pancreas (171 samples, TCGA and GTEx databases)." (PMID 39000545, 2024). "The cell surface receptors GHR and DA also serve as targets for the highly effective GHR antagonist pegvisomant and for DA used primarily in an adjunctive treatment setting, respectively, but there is less evidence regarding their use as markers of tumor aggressiveness." (PMID 36545335, 2022). "Together, our data suggest that, in agreement with CA STAT signalling identified using IPA, the GHR pathway may be upregulated in GBMGHR high tumours at several levels: GHR transcription (GHRhigh vs. GHRlow PDCL), GHR protein stabilization and GHR signalling (SOCS2 downregulation)." (PMID 35808822, 2022). "Our study suggested that GHR might also contribute to tumor development in BLCA." (PMID 35909123, 2022). "Furthermore, knockdown of GHR inhibited tumor growth in vivo." (PMID 31725956, 2020). "Furthermore, knockdown of growth hormone receptor inhibits tumor growth in vivo." (PMID 31725956, 2020). "The total disease burden and tumor burden of the Igf1r+/− and WT mice were also measured because previous studies show that disease burden is significantly reduced in established mouse models of longevity, e.g., dietary restriction, Ames Dwarf mice, and growth hormone receptor knockout mice." (PMID 22132081, 2011). "GHR antagonism rescued gemcitabine resistance and improved gemcitabine efficacy in vivo, wherein the GHRA-treated groups had marked tumor retraction in multiple mice of both sexes." (PMID 39000545, 2024). "Therefore, inhibition of GHR activity may be effective in inhibiting tumor cell proliferation." (PMID 39459020, 2024). "As the corresponding hormone receptors, GHR and IGFR play important roles in cell senescence and tumor formation." (PMID 36945046, 2023). "Studies from different groups also demonstrated that GH/GHR signaling stimulates the proliferation of HCC cells in vitro and the growth of HCC tumor xenografts in nude mice." (PMID 36276070, 2022). "Our results showed that silence of GHR inhibited the growth of SGC‐7901 and MGC‐803 cells, and tumour development in mouse xenograft model." (PMID 33492754, 2021). "To confirm the role of GHR and ABCG2 knockdown on tumor growth, we performed IHC and immunoblot analyses on the xenograft tumors for key markers involved in cell proliferation, apoptosis, and EMT." (PMID 30617282, 2019). "The link between the IGF1R‐PTPN1 proteins is known: literature data indicate a crucial role of PTPN1 as a tumour suppressor, able to negatively regulate multiple pathways of cell growth directly through IGF1R and IR, or indirectly through leptin receptor GHR." (PMID 29577582, 2018). "While the mRNA expression levels of GHR, IGF1 and IGF1R were increased in non-tumor tissues, they were downregulated in the tumors." (PMID 28710407, 2017). "GHR upregulation may be part of the tumorigenic process, since GHR expression is higher in cancerous prostate cell lines than in normal prostatic cell lines, and GHR immunoreactivity in the prostatic epithelium of TAg rodents increases in parallel with tumor development." (PMID 25580121, 2014). "The study also focused on tumor-intrinsic GHR expression, without considering interactions with stromal, immune, or extracellular matrix components." (PMID 41515995, 2025).
tumor (continued). "Conversely, TQ treatment resulted in the downregulation of several genes overexpressed in GBM cells, including potential oncogenes like AEBP1, MIAT, GHR, LMO1, ELF3, and genes involved in tumor proliferation and migration such as EPHA4, COL3A1, PCDH10, ROBO1, ADAMTS5, PCDH18, ST8SIA1." (PMID 39874307, 2025). "A limitation of the present study is the absence of in vivo validation demonstrating that GHR antagonism in combination with chemotherapy improves tumor control, survival, or treatment tolerability." (PMID 41515995, 2025). "Notably, the important role of growth hormone (GH)/growth hormone receptor (GHR) signaling in HCC development and tumor burden has been recently described by our group." (PMID 36473155, 2022). "HCC patients with lower GHR hepatic expression exhibited significantly higher frequency of patients with AFP> 100 ng/ml (76.5% vs. 23.5%; p = 0.048); tumor size >5cm (82% vs. 18%; p = 0.02); vascular invasion (85.5% vs. 14.5%; p = 0.002), and advanced TNM stage (80.6% vs. 19.4%; p = 0.01)." (PMID 36374927, 2022). "High levels of expression of GHR were documented in the four groups and, as suspected, treatment with PEGV-100 did not affect the basal tumor levels of GHR." (PMID 36276070, 2022). "Moreover, we assessed differences in biomarker levels, tumor extension, histological granulation pattern, MIB-1 staining and growth hormone receptor (GHR) phenotypes in patients with different long-term outcomes." (PMID 36042253, 2022). "Other genes annotated on chromosome 20 are involved in mammary gland metabolism (GHR, OXCT1), antibody production and phagocytosis of bacterial cells (C6, C7, C9, C1QTNF3), tumor suppression (DAB2), involution of mammary epithelium (OSMR) and cytokine regulation (PRLR)." (PMID 25658712, 2015). "Additionally, this work focuses on tumor-intrinsic GHR expression and does not account for the complex interactions within the tumor microenvironment, including crosstalk with stromal cells, immune components, and ECM interactions." (PMID 40806252, 2025). "Therefore, GHR expression, along with IGF1 and IGF1R levels, may provide a more comprehensive understanding of GH signaling in tumor progression." (PMID 40806252, 2025). "Furthermore, these two cases shared a common five-member mutant cell surface receptor signature as well (DSCAM, IGSF21, GHR, GRINA2 and RP1), suggesting that they may also have been involved in the massive antitumoral response to the primary tumor." (PMID 36980598, 2023). "Human tumor transcriptomic data for 377 HCC patients also show a positive correlation of multiple ABC transporters including the ABCB1, ABCC3, ABCC9 and ABCG2 with GHR expression, while ABCC1,ABCC4 and ABCG1 levels correlated with IGF1R expression, confirming our in vivo observations." (PMID 35865483, 2022). "Interestingly, we also found that a small portion of genes was not consistently expressed in different tumor cell lines, such as GHR and MSRB3." (PMID 35719407, 2022). "In conclusion, by using 1HC method, we found that down-regulation of GHR and its downstream pathway was correlated to the development of HCV-related HCC, that was associated with tumor aggressiveness and worse prognosis, irrespective of the functional status of liver." (PMID 36374927, 2022). "RNA expression of GH, GHR, IGF1, IGF1R, and PRLR is also detected using qPCR, and IGF1 production in tumor cells is markedly lower in mouse tumor cells but not in human tumor cells." (PMID 39000545, 2024).
metabolic disease (6 papers, 2020 to 2025). A congenital disorder (due to inherited enzyme abnormality) or acquired (due to failure of a metabolically important organ) disorder resulting from an abnormal metabolic process. "Disrupted GH/GHR in mice results in multiple metabolic disorders." (PMID 36499637, 2022). "We next determined whether hepatic GHR levels were altered in metabolic disorder mouse models." (PMID 34373742, 2021).
endocrine disease (2 papers, 2017 to 2022). "However, in the study, Ayling indicates that dominant GHR mutations should be looked for in children with normal GHBP levels and low body heights; that is, in children with no previous suspected endocrinopathy." (PMID 35627241, 2022).
infection (2 papers, 2013). The state of being infected such as from the introduction of a foreign agent such as serum, vaccine, antigenic substance or organism. "Likewise, the Trefoil Factor Initiated Mucosal Healing pathways were significantly suppressed in early stage of infection, more specifically, PTK2, GHR, RHOA, CTNNB1, MAPK3, and SHC1 genes." (PMID 24349118, 2013).
skeletal dysplasia (1 paper, 2024). Any Mendelian diseases that affects growth and development of the skeleton. "Together, these data point to reduced hepatic GHR expression and GHI as potentially contributing to growth failure and skeletal dysplasia seen in the Tmem263-KO animals." (PMID 38241182, 2024).
GHR also shares sentences with these, for which no sentence is quoted: acne (4 papers); coronary heart disease (4); genetic disorder (4); hypopituitarism (4); type 1 diabetes (4); colon carcinoma (3); Stroke (3); autosomal recessive hereditary disease (2); benign tumors (2); Cachexia (2); dementia (2); heart disease (2); inflammatory bowel disease (2); Liver diseases (2); neurodegenerative disease (2); 3-M syndrome (1); Acute hepatic failure (1); acute myeloid leukemia (1); Age-related cataract (1); albuminuria (1); alcohol (1); allergic asthma (1); alpha-mannosidosis (1); Alzheimer disease (1); amyotrophic lateral sclerosis (1); angiosarcoma (1); bacterial infection (1); bladder urothelial carcinoma (1); bovine tuberculosis (1); Brachycephaly (1).
A further 63 diseases each share a sentence with GHR in 1 paper.